DNAJB6 (DnaJ heat shock protein family (Hsp40) member B6)
Diseases named in the same sentence as DNAJB6 in open-access papers (continued):
Sharing a sentence is not in itself a finding about the gene and the disease.
tumor (17 papers, 2008 to 2024). "Survival and Cox regression analyses were used to identify that DNAJB6 mRNA and tumor stage were independent risk factors for the survival and prognosis of patients." (PMID 39335495, 2024). "uPAR and heat shock proteins HSP70 and MRJ (DNAJB6) have been implicated in tumor growth and metastasis." (PMID 25175595, 2014). "Based on DNAJB6 mRNA expression and survival data, univariate and multivariate Cox regression analyses were performed to explore independent risk factors for overall survival and progression-free survival, including age, gender, smoking status, and tumor stage, respectively." (PMID 39335495, 2024). "The proportion of tumor-infiltrating immune cells significantly differed between high and low DNAJB6 expression." (PMID 39335495, 2024). "In TCGA datasets, DNAJB6 expression was markedly upregulated in 59 LUAD tumor samples than that in paired normal tissues." (PMID 39335495, 2024). "Multivariate Cox regression analysis showed that DNAJB6 mRNA level (Hazard ratio = 1.517; p = 0.009) and tumor stage (Hazard ratio = 1.620; p < 0.001) were independent risk factors for overall survival." (PMID 39335495, 2024). "The IRS of DNAJB6 in tumor samples was significantly higher than in adjacent normal lung samples, and DNAJB6 staining was strong (IRS ≥ 6) in 19 (32.8%) tumor samples." (PMID 39335495, 2024). "DNAJB6 mRNA expression (Hazard ratio = 1.522; p = 0.041) and tumor stage (Hazard ratio = 1.345; p < 0.001) were independent risk factors for progression-free survival." (PMID 39335495, 2024). "We performed IHC assays to detect the expression of DNAJB6 and Ki67 in tumor tissues and found that DNAJB6 and Ki67 were markedly downregulated in the shDNAJB6 group." (PMID 39335495, 2024). "DNAJB6 is an HSP40 family protein that has significant influence on the inhibition of tumour growth and metastasis." (PMID 33594759, 2021). "Studies have demonstrated that DNAJB4 (HLJ1) and DNAJB6 (MRJ) function as tumor suppressors in multiple types of cancer." (PMID 33966034, 2021). "Similar tumor suppressing activity has been well documented for another HSP40 members—DNAJB6, overexpression of which reduces malignancy and is responsible for partial reversal of the mesenchymal phenotypes in breast cancer, in vitro and in vivo." (PMID 28914774, 2017). "The function and expression of DNAJB6 in tumor cells showed obvious tissue-specific changes." (PMID 39335495, 2024). "Therefore, further experimental studies are required to prove the role of DNAJB6 in tumor immunotherapy." (PMID 39335495, 2024). "It has been reported that DnaJB6 (MRJ) has an important role in controlling and assessing the development and outcome of multiple cancers, although more detailed studies on the role of MRJ in tumor progression are needed." (PMID 35570564, 2022). "Interestingly, the expression of other DNAJ–HSP40 proteins (DNAJB4 and DNAJB6) that are known as tumor suppressors was increased in metastatic TNBC cell lines." (PMID 33966034, 2021). "MRJ (DNAJB6), another example of subclass B, has two splice variants, a large isoform a [MRJ(L)] and a smaller variant b [MRJ(S)] which may have tumor suppressive functions." (PMID 28914774, 2017). "Considering that tumor stage is a high-risk factor for LUAD prognosis in clinical practice, this result not only suggests that DNAJB6 mRNA may be used as a predictive biomarker for LUAD prognosis but also indicates the rationality of bioinformatic analysis and the cohort in this study." (PMID 39335495, 2024). "In vitro and in vivo studies demonstrated that circPLEKHM3 played an anti-tumor role by sponging miR-9 to enhance the tumor-suppressive effect of BRCA1, DNAJB6, and KLF4, and consequently inactivated the AKT signaling in EOC." (PMID 36428803, 2022). "Six genes (DNAJB6, RB1, VIMP/SELENOS, STEAP3, BACH1, and ALOX12) had a consistent mRNA expression level in tumor samples and prognosis in the univariate Cox analysis." (PMID 34075060, 2021).
tumor (continued). "The expression levels of DNAJB1, DNAJB5, DNAJB6, DNAJB11, DNAJB12, DNAJB13, and DNAJB14 were significantly upregulated in the tumor tissues." (PMID 32984053, 2020). "That is, either of the two mechanisms will lead to release more sponged miR-9 into tumor tissues, which subsequently reduces the endogenous suppressive effect of BRCA1, DNAJB6 and KLF4." (PMID 31623606, 2019). "DNAJB6 expression and function in LUAD were explored using immunohistochemistry, Western blotting, proliferation, cell cycle analysis, RNA sequencing, and xenograft tumor assays." (PMID 39335495, 2024). "DNAJB6, a major member of the DNAJ/HSP40 family, plays an important role in tumor development." (PMID 39335495, 2024). "DNAJB6 protein levels were higher in LUAD tumor tissues than in normal tissues." (PMID 39335495, 2024). "However, no reports exist on the DNAJB6 and tumor immune signaling pathways." (PMID 39335495, 2024).
cancer (16 papers, 2017 to 2024). A tumor composed of atypical neoplastic, often pleomorphic cells that invade other tissues. "Functional enrichment analysis based on the TCGA database provided information on the biological processes associated with cancer promotion by DNAJB6 in LUAD." (PMID 39335495, 2024). "The variable roles of DNAJB6 underscore its significance as a potential biomarker and therapeutic target in specific cancer contexts." (PMID 38562143, 2024). "DNAJB6, represented by its isoforms DNAJB6a and DNAJB6b, engages in a range of cellular activities and contributes to diverse health conditions, including cancer." (PMID 38562143, 2024). "DNAJB6 is a gene target of miR-632 in cancer and plays a critical role in blocking epithelial-to-mesenchymal transition by inhibiting the Wnt/β catenin pathway." (PMID 37894814, 2023). "Previous studies have reported that DNAJB6 is involved in cancer cell proliferation, EMT, and metastasis by regulating the Wnt/β-catenin signaling pathway in various cancers." (PMID 36499297, 2022). "In colorectal cancer cells, knockdown of DnaJB6 suppresses the cancer metastasis by decreasing IQ-domain GTpase-activating protein 1 and phosphorylated ERK." (PMID 31878360, 2019). "Notably, RNA-seq data of human cancers were extracted from the TCGA database, and the expression levels of DNAJB6 in various human cancers were analyzed." (PMID 39335495, 2024). "Age, gender, cancer stage, smoking history, and DNAJB6 expression were included in the nomograms." (PMID 39335495, 2024). "DNAJB6 is involved in the pathogenesis of many different types of cancers." (PMID 39451243, 2024). "Studies suggest that export of DnaJB11 enhances extracellular proteostasis, that intercellular movement of DnaJB1 or DnaJB6 enhances the proteostasis capacity in recipient cells, whereas the import of DnaJB8 increases resistance to chemotherapy in recipient cancer cells." (PMID 36581212, 2023). "Importantly, some DNAJB proteins, including DNAJB1/HDJ1, DNAJB4/HLJ1, DNAJB6/MRJ, DNAJB8, DNAJB9/MDG1/ERdj4, DNAJB11/ERdj3/HEDJ, and DNAJB12, are implicated in cancer progression." (PMID 34948322, 2021). "MiR-632 is an important epigenetic regulator of DNAJB6 (a member of the HSP40 family) and of the epithelial–mesenchymal transition in cancer stem cells." (PMID 32961817, 2020). "DNAJ member B6 (DnaJB6) has also been elucidated as a poor prognostic factor for CRC patients, where its overexpression was observed in 39% of the CRC patients, especially in those at the stage of cancer IV compared to the stages I–III." (PMID 31878360, 2019).
neurodegenerative disease (10 papers, 2015 to 2025). A disorder of the central nervous system characterized by gradual and progressive loss of neural tissue and neurologic function. "The results reinforce the pivotal role of DNAJB6 in assisting in the folding of divergent client proteins related to neurodegenerative diseases." (PMID 38110916, 2023). "They primarily involved mechanisms well-established in neurodegenerative diseases, such as synaptic dysfunction and protein misfolding, and with shared directionality of changes for the genes involved, such as ELAVL4 and DNAJB6 (upper part)." (PMID 41318503, 2025).
infection (5 papers, 2012 to 2024). The state of being infected such as from the introduction of a foreign agent such as serum, vaccine, antigenic substance or organism. "While numerous Hsp40 proteins have been shown to play key roles in the life cycles of viruses, little is known about the role of DNAJB6 in infections of viruses except HIV-2." (PMID 23133382, 2012). "Consistent with the idea that chaperone proteins may play a role in infection by all herpesviruses is the fact that HCMV primase UL70 has recently been shown to interact with the Hsp40 family member DNAJB6." (PMID 24064794, 2013). "In HEK293 cells, DNAJB6 mRNA levels increased over the time course of JEV infection MOI =1, while DNAJB6 protein levels decreased over the time course of infection and were lower overall compared with mock-infected cells." (PMID 31739611, 2019). "It is possible that DNAJB6 interacts with HCMV proteins other than UL70, leading to a modulation of viral DNA replication and infection as observed in our experiments." (PMID 23133382, 2012). "Although the function of DNAJB6 in macrophages has been shown to be a cellular stress response to regulate the different stages of viral replication and infection, the role of DNAJB6 in macrophage polarization has never been investigated." (PMID 39451243, 2024). "DNAJB6, a member of the DnaJ/Hsp40 family, has been shown to play a role in the life cycle of HIV-1, RSV HIV-2, and Human Cytomegalovirus, and more recently has been reported to be involved in dengue virus infection." (PMID 31739611, 2019). "It is conceivable that controlling the differential expression of DNAJB6 proteins, mediated by alternative splicing, may represent a novel mechanism for the regulation of HCMV replication and infection, by modulating the cellular localization of UL70." (PMID 23133382, 2012).
neuromuscular disease (1 paper, 2020). "In this review, we cover mutations in DNAJB6, DNAJB2, αB-crystallin (CRYAB, HSPB5), HSPB1, HSPB3, HSPB8, and BAG3, and discuss the molecular mechanisms by which they cause neuromuscular disease." (PMID 32093037, 2020).
DNAJB6 also shares sentences with these, for which no sentence is quoted: Corticobasal Degeneration (2 papers); lung carcinoma (2); melanoma (2); Parkinson’s (2); progressive supranuclear palsy (2); viral infection (2); acute myeloid leukemia (1); amyotrophic lateral sclerosis (1); Atrophy (1); autosomal dominant disease (1); autosomal recessive spastic ataxia (1); breast invasive carcinoma (1); central nervous system cancer (1); cholangiocarcinoma (1); collagenopathy (1); colon adenocarcinoma (1); congenital muscular dystrophy (1); COVID-19 (1); dilated cardiomyopathy (1); distal motor neuropathy (1); Emery-Dreifuss muscular dystrophy (1); familial amyotrophic lateral sclerosis (1); fibrosis (1); Filaminopathy (1); head and neck squamous cell carcinoma (1); idiopathic cardiomyopathy (1); laminopathy (1); leukemia (1); lung squamous cell carcinoma (1); metabolic disease (1).
A further 15 diseases each share a sentence with DNAJB6 in 1 paper.